RAB6A (RAB6A, member RAS oncogene family)
Description:
The small GTPases Rab are key regulators of intracellular membrane trafficking, from the formation of transport vesicles to their fusion with membranes. Rabs cycle between an inactive GDP-bound form and an active GTP-bound form that is able to recruit to membranes different sets of downstream effectors directly responsible for vesicle formation, movement, tethering and fusion. RAB6A acts as a regulator of COPI-independent retrograde transport from the Golgi apparatus towards the endoplasmic reticulum (ER). Has a low GTPase activity. Recruits VPS13B to the Golgi membrane. Plays a role in neuron projection development (Probable).
Synonyms: RAB6
Tractability: Small molecule: a structure with a bound ligand is known; it has a binding pocket of medium quality. Antibody: UniProt places it where antibodies can reach, with high confidence; its Gene Ontology location is reachable by antibodies, with high confidence. PROTAC: ubiquitination databases record sites on it; its protein half-life has been measured; a small molecule that binds it is known.
Target class: Enzyme; Hydrolase
Gene: Protein-coding gene on chromosome 11 (73,675,638 to 73,761,465, reverse strand). Ensembl gene ENSG00000175582.
Subcellular location: Golgi apparatus membrane; Cytoplasmic vesicle, secretory vesicle, acrosome membrane; Golgi apparatus membrane (Isoform 1); Golgi apparatus membrane (Isoform 2)
Subcellular location (Human Protein Atlas): Golgi apparatus; Basal body
Pathways (Reactome):
Vesicle-mediated transport: COPI-independent Golgi-to-ER retrograde traffic; RAB GEFs exchange GTP for GDP on RABs; Retrograde transport at the Trans-Golgi-Network; TBC/RABGAPs
Immune System: Neutrophil degranulation
Metabolism of proteins: RAB geranylgeranylation
Signal Transduction: Pre-NOTCH Processing in Golgi
Gene Ontology:
Molecular function: G protein activity; GTP binding; GTPase activity; myosin V binding; protein binding; protein domain specific binding
Biological process: antigen processing and presentation; early endosome to Golgi transport; peptidyl-cysteine methylation; protein localization to Golgi apparatus; protein localization to Golgi membrane; retrograde vesicle-mediated transport, Golgi to endoplasmic reticulum; intra-Golgi vesicle-mediated transport; minus-end-directed organelle transport along microtubule; neuron projection development; retrograde transport, endosome to Golgi
Cellular component: cytoplasmic vesicle; cytosol; endosome to plasma membrane transport vesicle; extracellular exosome; Golgi apparatus; Golgi membrane; membrane; trans-Golgi network; acrosomal membrane; endoplasmic reticulum membrane; plasma membrane; secretory granule membrane; trans-Golgi network membrane
Genetic constraint (gnomAD): Loss-of-function variants: 3 observed, 13.89 expected, observed/expected ratio (o/e) 0.22, 90% interval 0.097 to 0.56. The upper end of that interval is the gene's LOEUF score, 0.56, which puts it in group 2 of 6, group 1 being the genes least tolerant of losing a copy. Missense variants: 44 observed, 126.37 expected, observed/expected ratio (o/e) 0.35, 90% interval 0.27 to 0.45. Synonymous variants: 41 observed, 44.34 expected, observed/expected ratio (o/e) 0.92, 90% interval 0.72 to 1.2.
Homologues: Orthologues: dog RAB6A (99% identical), macaque RAB6A (99% identical), rabbit RAB6A (99% identical), mouse Rab6a (99% identical), chimpanzee RAB6A (99% identical), zebrafish rab6a (98% identical), tropical clawed frog rab6a (98% identical), guinea pig RAB6A (90% identical), Drosophila melanogaster Rab6 (88% identical), rat Rab6a (82% identical), pig RAB6A (77% identical), Caenorhabditis elegans rab-6.1 (75% identical). Paralogues in human: RAB6B (90% identical), RAB6D (90% identical), RAB6C (89% identical), RAB41 (64% identical), RAB26 (41% identical), RAB8B (41% identical), RAB8A (40% identical), RAB37 (39% identical), RAB5A (39% identical), RAB10 (39% identical), RAB5B (38% identical), RAB5C (38% identical), and 56 more.
Diseases named in the same sentence as RAB6A in open-access papers:
RAB6A is named in the same sentence as 56 diseases in open-access papers, as found by Europe PMC text mining. Sharing a sentence is not in itself a finding about the gene and the disease. The quoted sentences say what the papers report.
Parkinson disease (13 papers, 2015 to 2025). A progressive degenerative disorder of the central nervous system characterized by loss of dopamine producing neurons in the substantia nigra and the presence of Lewy bodies in the substantia nigra and locus coeruleus. "Several implicated host proteins—notably HTRA1, MAPT, and RAB6A—are highly expressed in the cerebellum and basal ganglia, aligning with observed clinical features such as ataxia, opsoclonus‐myoclonus, and parkinsonism." (PMID 40259581, 2025).
breast carcinoma (7 papers, 2016 to 2025). "To investigate the possible molecular mechanisms underlying the reduced STAT5 activation observed upon Rab6a deletion, we took advantage of T47-D, a human breast cancer-derived cell line commonly used for studying PRL-induced signaling events." (PMID 32895290, 2020). "We discovered that a considerable number of women with breast cancer and vision disturbance had serum anti-TULP1 AAbs, often coexisting with other anti-retinal AAbs, including a case of anti-recoverin and anti-Rab6A being present in the same patient." (PMID 40141211, 2025).
pulmonary fibrosis (3 papers, 2020 to 2024). Chronic progressive interstitial lung disorder characterized by the replacement of the lung tissue by connective tissue, leading to progressive dyspnea, respiratory failure, or right heart failure. "Animal studies have also demonstrated that elevated levels of RAB6A RNA and protein were correlated to the development of idiopathic pulmonary fibrosis." (PMID 38275610, 2024).
HIV-1 infection (2 papers, 2009 to 2012). The type species of lentivirus and the etiologic agent of acquired immunodeficiency syndrome (AIDS). "siRNA constructs specific for viral Tat and a cellular target, Rab6A, provided positive controls based on recent reports that these siRNA were able to efficiently inhibit HIV-1 infection." (PMID 19788744, 2009). "Some of the factors of vesicular trafficking may be potentially involved in the early stage of HIV-1 infection: the functional genomic screening of factors involved in HIV-1 infection showed that the vesicular RAB6A protein is important for the late phase of reverse transcription in infected cells." (PMID 22889230, 2012).
prostate carcinoma (2 papers, 2016 to 2022). A carcinoma that arises from epithelial cells of the prostate gland. "We previously demonstrated in prostate cancer cells that the Golgi-specific GTPase Rab6a is involved in fragmentation of the Golgi through cooperation with NMIIA11." (PMID 27535804, 2016).
bile duct cancer (1 paper, 2025). "Various RAB genes have been linked to tumors, including RAB27A, which serves as a predictive indicator for pancreatic ductal adenocarcinoma; RAB13 and RAB3D, which are elevated in pan-cancer; and RAB1A and RAB6A, which have significant functions in rectal cancer and bile duct cancer, respectively." (PMID 40177653, 2025).
Chlamydia infections (1 paper, 2009). "Taken together, our data show Rab6A and Rab11A are essential for Chlamydia-induced Golgi fragmentation and further strengthens the hypothesis that Golgi fragmentation can influence the outcome of Chlamydia infections." (PMID 19816566, 2009).
developmental delay (1 paper, 2025). "Biallelic variants in RABGAP1, the GTPase‐activating protein of RAB6A for retrograde transport from Golgi to ER, were reported in patients with global developmental delay, microcephaly, bilateral sensorineural hearing loss, seizures, corpus callosum dysgenesis, and facial dysmorphism." (PMID 39420677, 2025).
epilepsy (1 paper, 2021). A brain disorder characterized by episodes of abnormally increased neuronal discharge resulting in transient episodes of sensory or motor neurological dysfunction, or psychic dysfunction. "Alternatively, Rab6A- astrocytes may represent a particular type of astrocytic reactivity involving loss of general astrocyte features, such as GS expression, which is also downregulated, e.g., in epilepsy." (PMID 33466322, 2021). "Freshly fixed human cortex was obtained from three patients during epilepsy surgery and labelled for Rab6A or Rab6A/GFAP." (PMID 33466322, 2021).
microcephaly (1 paper, 2024). A congenital or acquired developmental disorder in which the circumference of the head is smaller than normal for the person's age and sex. "It has been confirmed by mouse gene knockout experiments that the reduced expression of RAB6A can lead to microcephaly and neuronal dysplasia." (PMID 39691419, 2024).
teratoma (1 paper, 2010). A non-seminomatous germ cell tumor characterized by the presence of various tissues which correspond to the different germinal layers (endoderm, mesoderm, and ectoderm). "It is noteworthy that alterations of several potential oncogenes (such as RAB6A) were also seen in these hESC lines, which induced only benign tumors in the mouse teratoma assay." (PMID 20428235, 2010).
Thrombocytopenia (1 paper, 2025). A reduction in the number of circulating thrombocytes. "Finally, we confirmed that the combination of adiponectin with thrombopoietic agents promotes the transport of c‐Mpl to the cell surface by enhancing the expression of Rab6A GEFs, which might be a clinical treatment for alleviating thrombocytopenia." (PMID 40558825, 2025).
infection (24 papers, 2009 to 2024). The state of being infected such as from the introduction of a foreign agent such as serum, vaccine, antigenic substance or organism. "Rab6a is required for efficient infection for HPV16, HPV18, and HPV5, and the C-terminus of L2 of all three HPV types can bind purified Rab6a." (PMID 39431827, 2024). "Parvovirus capsids have been shown to associate with Rab6a secretory vesicles, and genetic screens have shown that HIV requires Rab6a for infection." (PMID 39136459, 2024). "We conducted immunoprecipitation experiments using lysates from cells expressing 3x-FLAG-Rab6A (wild-type) or -Rab6A (T27N) after infection with wild-type L. pneumophila." (PMID 33760868, 2021). "Rab6a also plays important roles in infection by other viruses." (PMID 39431827, 2024). "Rab6a depletion also inhibited infection by HPV18 and HPV5 PsVs." (PMID 39431827, 2024). "Consistent with this view, HPV-BICD2 association and HPV-dynein association require Rab6a at 16 h post-infection (hpi) but not at earlier times, and Rab6a is critical for exit of HPV from the TGN during entry." (PMID 39431827, 2024). "We previously reported that Rab6a is required for infection by HPV16 PsV, but the specific role of Rab6a in HPV entry is unknown." (PMID 39431827, 2024). "To assess the effect of the Rab family on RSV replication, we depleted Rab1a, Rab2a, Rab4a, Rab5a, Rab6a, Rab7a, Rab8a, Rab9a, and Rab11a by treating A549 cells with specific siRNAs (or control siRNA) for 24 h, followed by infection with purified RSV A2 and incubation for another 36 h." (PMID 33504607, 2021). "The efficient recruitment of Sec22b-containing ERDVs to the LCV was observed at 1 h post infection in Rab6A- and Rab33B-silenced cells, similar to mock-treated cells, implying that loss of both Rab proteins does not affect the uptake of L. pneumophila or the remodeling of the LCV." (PMID 33760868, 2021). "Both endogenous and mRFP-tagged Rab6A and Rab33B were detected in a significant fraction of LCVs, and the recruitment of these Rabs to the LCVs are increasing at 2 h post infection, corresponding to the time when ER protein calnexin starts to accumulate on the LCV." (PMID 33760868, 2021). "Rab1 is upregulated in the kidney of red drum in response to intracellular bacteria Edwardsiella tarda during 4- to 24-h time periods of infection, and Rab-1A, Rab-6A, and Rab-10 proteins have been upregulated persistently in the liver of gilthead sea bream profile after confinement exposures." (PMID 25563603, 2015). "It is possible that a higher expression of Rab6A leads to an increase in recycling of endosomes, removing the potential for WSSV to interact with Rab7, which in turn inhibits infection and thereby leads to resistance." (PMID 26797629, 2016). "Silencing of Rab6A did not significantly affect Rab33B recruitment to the LCV at 4 h post infection (top row)." (PMID 33760868, 2021).
tumor (11 papers, 2004 to 2022). "Rab6A and related genes, the network accurately separated tumours with 100% accuracy in our study, are involved in intracellular transport." (PMID 15579197, 2004).
metabolic disorders (1 paper, 2024). "The implications of the genetic mutations of RAB6A and SIDT2 are unknown in our population of interest but have been associated with pulmonary, cardiac, and metabolic disorders." (PMID 38275610, 2024).
RAB6A also shares sentences with these, for which no sentence is quoted: cancer (19 papers); viral infection (7); Alzheimer disease (6); lung carcinoma (5); bacterial infection (2); melanoma (2); non-small cell lung carcinoma (2); pancreatic cancer (2); Parkinson (2); amyotrophic lateral sclerosis (1); Ataxia (1); cardiomyopathy (1); colon cancer (1); colorectal cancer (1); COVID-19 (1); cyst (1); diabetes (1); enterovirus infection (1); fungal infection (1); hepatocellular carcinoma (1); idiopathic pulmonary fibrosis (1); Lewy body dementia (1); liver cancer (1); liver disease (1); Macrothrombocytopenia (1); malaria (1); mental disorder (1); metabolic bone disorder (1); myeloma (1); neurodegenerative disease (1).
A further 11 diseases each share a sentence with RAB6A in 1 paper.